IL6 (interleukin 6)
Diseases named in the same sentence as IL6 in open-access papers (continued):
Sharing a sentence is not in itself a finding about the gene and the disease.
COVID-19 (continued). "Although a significant elevation of serum IL-6 and IL-17 levels were observed and predicted a poor clinical outcome in critical COVID-19 cases, there was neither correlation between their levels nor significant difference between their ROC-AUC." (PMID 41184328, 2025). "This assumption could be supported by the observations of increased levels of pro-inflammatory cytokines, mainly IL-6, but also TNF, which although lower when compared to those in adults’ COVID-19, are still elevated above the normal levels." (PMID 39940694, 2025). "Our results show that combined high levels of IL-6 and IL-10 in patients with pneumonia can have a significant impact on clinical practice by differentiating between COVID-19 and non-COVID-19 pneumonia." (PMID 40508859, 2025). "The spike protein has been shown to trigger prolonged expression of cell adhesion markers and the release of various cytokines and chemokines, such as interleukin-6 (IL-6), tumor necrosis factor-alpha (TNF-α), and interleukin-1β (IL-1β), which are commonly observed in severe COVID-19 cases." (PMID 41012643, 2025). "Interestingly, while several studies have reported a significant positive correlation between IL-6 and NLR in patients with COVID-19, particularly in severe or critically ill populations, we did not observe such an association in our cohort." (PMID 40430148, 2025). "Elevated levels of IL-6 and TGF-β have been correlated with severe lung inflammation and fibrosis, as well as dysregulation of the kynurenine pathway (KP), a TRP metabolic pathway consistently disturbed in COVID-19 patients." (PMID 40949107, 2025). "Patient data, including COVID-19 history, clinical characteristics, and comorbidities, were collected, and laboratory parameters were analyzed, including inflammatory markers like C-reactive protein (CRP) and interleukin 6 (IL-6)." (PMID 41210029, 2025). "In the COVID-19+ group, as expected, significantly increased levels of proinflammatory cytokines/chemokines including INF-α2, INF-γ, MCP-1, IL-6, IL-12p70, IL-17A, IL-18, IL-23 and IL-33 were detected, while the level of IL-10, an anti-inflammatory cytokine was also elevated as compared to controls." (PMID 40303405, 2025). "Traditional inflammatory markers, including C-reactive protein (CRP), Interleukin-6 (IL-6), ferritin, and composite indices such as the Neutrophil-to-Lymphocyte Ratio (NLR) and the Prognostic Nutritional Index (PNI), have been studied extensively in COVID-19." (PMID 39857810, 2025). "Meta-analyses of IL-6 and IL-10 levels in COVID-19 patients with and without organ failure provide insights into the differences between these two groups." (PMID 41585373, 2025). "Increased levels of circulating cytokines (among which IL-6 and IL-17) and growth factors (among which VEGF and bFGF) may be detected in vaccinees up to one year after vaccination with anti-COVID-19 mRNA Comirnaty." (PMID 41375068, 2025). "The cytokine storms are characterized by significant induction of specific cytokines such as IL-6, IL-2, IL-7, GM-CSF, and IFN-γ in COVID-19 patients, which are different from other respiratory viruses with the increase in cytokines such as IL-2, IL-10, IL-4, or IL-5." (PMID 41002992, 2025). "Higher cytokine level, especially interleukin 6 (IL-6) independently increased the risk of ICD shocks and is a predictor of SCD, however, data from the period of the COVID-19 pandemic (a systemic inflammatory disease) are not clear." (PMID 41574188, 2025). "Patients with severe COVID-19 history showed significantly higher sequential organ failure assessment and acute physiology and chronic health evaluation II scores, along with elevated APTT, PCT, IL-6, IL-1β, and IL-17 levels." (PMID 41305706, 2025).
COVID-19 (continued). "Numerousstudies have corroborated the inflammatory profile of COVID-19, with serum levels ofpro-inflammatory biomarkers, including LDH, CRP, D-dimer, and IL-6, beingsignificantly elevated upon admission in both critical and non-critical patientsacross multiple clinical trials." (PMID 40532042, 2025). "Few previous reports have measured changes in biomarkers before and after PMX-DHP treatment in COVID-19 patients, and none have found a significant reduction in IL-6 levels." (PMID 40084335, 2025). "Therefore, the correlation between high levels of IL-6 after acute SARS-CoV-2 infection and the evolution to long-COVID-19 seems to be clear." (PMID 39859366, 2025). "The cytokine profiles of COVID-19 and IPF show significant overlap, particularly in the elevation of profibrotic and proinflammatory mediators such as transforming growth factor-beta (TGF-β), interleukin-6 (IL-6), and tumor necrosis factor-alpha (TNF-α)." (PMID 40806851, 2025). "In both analyses, COVID-19 patients with organ failure showed significantly higher IL-6 and IL-10 levels than those without organ failure, with greater variability in IL-10 findings (I2 = 86%, P = 0.0006)." (PMID 41585373, 2025). "Increased levels of interleukins (IL-1 α, IL-7, IL-17, and IL-18) and chemokines (CCL11, and CXCL1) were found only in the COVID-19-only, whilst PLWH/COVID-19, had increased levels of four different interleukins (IL-5, IL-6, IL-9, and IL-15) and one chemokine (CXCL10) compared to COVID-19-only." (PMID 41516165, 2025). "Furthermore, the long-term persistence of high plasma levels of IL–1β, IL–6, and TNF in patients with COVID-19 symptoms opens up therapeutic options based on blocking the signaling of these cytokines." (PMID 40217938, 2025). "Similarly, regarding inflammatory cytokines, high levels of several cytokines, such as IL-1β, IL-2, IL-6, IL-7, IL-8, IL-10, CXCL10/IP-10, MCP-1, and TNF-α have already been described according to the severity of COVID-19." (PMID 39861879, 2025). "Post-COVID coagulation studies and inflammatory markers (CRP, D-dimer, IL-6) were not obtained as the decision for palliative care was made within 24 hours of COVID-19 diagnosis due to catastrophic neurological deterioration." (PMID 41503306, 2025). "In hospitalized patients with moderate-severe COVID-19, the DBS may be predictive of short-term clinical deterioration and may provide incremental prognostic information beyond IL-6 alone; confirmation in larger cohorts is warranted." (PMID 41322840, 2025). "We compared IL-1β, IL-1Ra and IL-6 mRNA production and release between IMHL patients with worsening SNHL after COVID-19 vaccination or infection (COVID (+)) with IMHL patients with worsening SNHL unrelated to COVID-19 (COVID (-))." (PMID 40329195, 2025). "IL-6 is a key inflammatory mediator in both PCC and severe COVID-19." (PMID 40429727, 2025). "The COVID-19/Self-RPD+ group frequently exhibited symptoms such as fever, body aches, nasal congestion, and olfactory disturbances and showed significantly higher IL-6 levels compared to the other groups." (PMID 40647649, 2025). "From a host genetic perspective, elevated levels of IL-6, IL-10, IL-13, MMP-7, ferritin, and D-dimer were observed in COVID-19 patients across all genotypes, with the CC genotype associated with the highest concentrations, suggesting a heightened inflammatory and pro-thrombotic state." (PMID 40733568, 2025). "The subsequent RuxCoFlam trial included COVID-19 patients with the same CIS cut-off (≥10) and yielded a similar response rate (71%), which was accompanied by a significant reduction of inflammation markers such as IFN-γ, IL-6, and IL-10 (p < 0.001 each)." (PMID 40430208, 2025). "The high level of IL-6 and IL-15 in PLWH/COVID-19 compared to COVID-19-only may produce an synergistic effect of pre-existing HIV-related immune activation and the acute immune response induced by SARS-CoV-2." (PMID 41516165, 2025).
COVID-19 (continued). "Cytokine storm including inflammatory cytokines IL-1β, IL-6, IL-17, and TNF-α could be provoked in moderate and severe COVID-19 patients." (PMID 41235116, 2025). "Regarding inflammation biomarkers, testosterone is inversely associated with interleukin-6 (IL-6) and C-reactive protein (CRP) in severe COVID-19, while testosterone and estradiol are similar in women with and without severe COVID-19." (PMID 40868247, 2025). "A leading, indirect pathway is inflammation-driven tumor promotion, particularly through IL-6/JAK–STAT3, IL-1β/NLRP3, TNF-α/NF-κB, and ELR+ CXC chemokines (e.g., IL-8/CXCL8), which are all engaged during COVID-19 and have established roles in lung tumor biology." (PMID 41440526, 2025). "Additionally, ozone reduces pro-inflammatory cytokines like IL-1, IL-6, and TNF-α, counteracting the hyperinflammation seen in severe COVID-19." (PMID 39860053, 2025). "Sepsis patients with a history of severe COVID-19 exhibited significantly higher IL-1β, IL-6, and IL-17 levels compared to those in the non-severe COVID-19 H group (P = .002, P <.001, and P <.001, respectively)." (PMID 41305706, 2025). "Compared to those without comorbidities, both cancer and immunosuppressed COVID-19 + patients had higher mean IL-6 concentrations after day 10 post symptom-onset, reaching above 60 pg/ml." (PMID 40489562, 2025). "In COVID-19, elevated TNF-α and IL-6 levels may suppress albumin synthesis and contribute to hypoalbuminemia." (PMID 40649865, 2025). "Specifically, the dysregulation of key cytokines like IL-6, TNF-α, and IL-1β during COVID-19 may directly interfere with thermoregulation, contributing to a diminished febrile response in CAM patients with prior COVID-19 infection." (PMID 40315194, 2025). "Our results also showed an increase in circulating IL-6, IL-10, and TNF-α levels in critical COVID-19 patients after 10 days of hospitalization, highlighting the importance of quantifying these cytokines longitudinally in COVID-19 patients." (PMID 40508859, 2025). "We observed higher levels of bilirubin, D-dimer, C-reactive protein, urea, and plasmatic cytokines, such as IL-1β, IL-6, IL-8, IL-10, IL-17A, IL-23, TNF-α, and IFN-α in individuals with the critical form of acute COVID-19 compared to individuals with the severe and/or moderate WHO clinical forms." (PMID 39861879, 2025). "Previous studies reported increased levels of IL-10, IL-6, and TNF-α in severe COVID-19 patients." (PMID 39856771, 2025). "Furthermore, it should be noted that patients with MIS-C had significantly higher levels of IL-1β, IL-6, IL-12, and TNF-α compared to patients with COVID-19." (PMID 40066463, 2025). "Pro-inflammatory cytokines, such as IL-6, IL-1β, and TNF-α, are known to induce F3 gene expression in both immune and non-immune cells, potentially contributing to the thromboembolic events observed in COVID-19 patients, particularly in severe cases." (PMID 41583455, 2025). "During SARS-CoV-2 infection, monocytes and macrophages detect viral particles and produce IL-6, IL-1β, and IFN-π/IL-27 through TLR, NF-κB activation, and inflammasome assembly, contributing to acute respiratory distress syndrome (ARDS) and severe COVID-19." (PMID 40934228, 2025). "Not only other cytokines, e.g., tumor necrosis factor-alpha, but also white blood cells have shown correlations with CRP, underscoring that CRP elevation in COVID-19 reflects a broader pro-inflammatory milieu rather than the action of IL6 alone." (PMID 41373577, 2025). "Similarly, inflammatory cytokines including IL-6, tumor necrosis factor-alpha (TNF-α), and CRP were elevated in patients with COVID-19 at baseline compared with levels in healthy controls in both the RoW and US studies." (PMID 40461100, 2025). "These included IL-6, TNF-α, CCL5, and CXCL2 with expression levels significantly surpassing those observed in SARS-CoV-2 and HKU4 controls, which were positively related to severity in COVID-19 patients." (PMID 40774246, 2025).
COVID-19 (continued). "Multiple studies show high levels of proinflammatory cytokines such as IL-1, TNF, IFNs, IL-6, IL-8, IL-18, IL-17α, G-CSF, and GM-CSF, as well as chemokines, such as MCP-1, IP-10, MIP-1α, CXCL10, CCL2, CCL4, CCL14, CCL19, and CCL25 in severe cases of COVID-19." (PMID 40076291, 2025). "The lowest IL-6 values were obtained in the group of COVID-19 patients who did not require hospitalization (2 pg/mL) and the highest in the ICU group (168.5 pg/mL)." (PMID 40756075, 2025). "In parallel, the pandemic has underscored the role of a dysregulated immune response, known as cytokine release syndrome (CRS), characterized by the overproduction of inflammatory cytokines like TNF-α, IL-6, IL-1β, and IFN-γ, which serve as inflammatory biomarkers of COVID-19." (PMID 40649865, 2025). "This study highlights the associations of the IL-6 rs1800796 (-572 G/C), IL-10 rs1800871 (-819 C/T), rs1800872 (-592 C/A) and CCL5 rs2107538 polymorphisms with fatal COVID-19 outcomes and elevation of cytokines (CCL-2, IL-6, IL-10 and CXC-L10) plays a crucial role in the pathogenesis of COVID-19." (PMID 40881695, 2025). "SARS-CoV2-infected monocytes and macrophages isolated from the lungs of COVID-19 patients produce huge amounts of pro-inflammatory cytokines such as IL-1β, TNF-α, IL-6, and IFN-α, β, and λ, which precedes the so-called cytokine storm and meanwhile abates the T-cell immune response." (PMID 41375068, 2025). "Patients with COVID-19 who developed ARDS had more IL-6 in their blood compared to those who did not have ARDS." (PMID 40895261, 2025). "In our study, all the examined ROTEM parameters, in line with IL-6 levels, were similar between the groups, and there were no indications of hypercoagulability in the COVID-19 group." (PMID 39940970, 2025). "In this study, interestingly, mild/asymptomatic COVID-19+ pregnant women exhibited significantly elevated levels of proinflammatory cytokines/chemokines such as INF-α2, INF-γ, MCP-1, IL-6, IL-12p70, IL-17A, IL-18, IL-23, and IL-33, and the anti-inflammatory cytokine IL-10." (PMID 40303405, 2025). "Among these, elevated levels of IL-6, CRP, and tumor necrosis factor alpha (TNFα) for one or more months after SARS-CoV-2 infection were indicators that patients may experience long-COVID-19 symptoms." (PMID 39859366, 2025). "In a similar study on Mexican COVID-19 patients during the early pandemic, the authors reported that IL-6 levels were significantly higher in the non-survivor group when compared with those in the survivors." (PMID 40508859, 2025). "The increased CRP together with elevated IL-6 and IL-15 in PLWH/COVID-19 could indicate hyperinflammation, further explaining the observed differences in the outcome of the COVID-19." (PMID 41516165, 2025). "In patients with COVID-19 and confirmed PE, very high CRP and IL-6 levels, together with extensive parenchymal involvement, identify a subgroup with a markedly increased risk of invasive mechanical ventilation and death, even when D-dimer and thrombus location are not strikingly different." (PMID 41463074, 2025). "Patients with comorbid COVID-19 and T2D exhibited significantly reduced expression of cytotoxic mediators (GZMB, perforin and IFN-γ) alongside elevated IL-6 levels compared with other groups, demonstrating a synergistic impairment of NK cell effector function in the dual-pathology cohort." (PMID 40471558, 2025). "In our study, well-documented hallmarks of severe COVID-19, such as lymphopenia, a higher neutrophil-to-lymphocyte ratio (NEU/LYM), and the proinflammatory cytokine storm including IL-6, IL-1β, IL-8, and TNF-α were observed in adult COVID-19 patients rather than pediatric patients." (PMID 39967737, 2025). "The proinflammatory cytokines IL-6 and IL-10 were significantly increased in COVID-19 patients compared to non-COVID-19 patients (p < 0.005), while TNF-α levels were lower in critically ill patients with COVID-19 pneumonia." (PMID 40508859, 2025).
COVID-19 (continued). "Furthermore, IL-6, CRP, D-dimer, and ferritin were significantly higher in severe forms of COVID-19." (PMID 40868247, 2025). "Notably, IL-6 and TNF-α blockade therapies, such as the IL-6 receptor inhibitor tocilizumab, have effectively reduced mortality in severe COVID-19 patients." (PMID 40643149, 2025). "Controlling diabetes and hyperglycemia in patients with COVID-19 resulted in the normalization of IL-1 and IL-6 levels after 14 days, irrespective of glucose levels." (PMID 40134446, 2025). "This appeared to be the case for IL-6, which was no longer predictive of COVID-19 health after removing individuals with inflammatory conditions." (PMID 41280118, 2025). "However, we did find that in COVID-19 patients, fibrinogen levels primarily correlated with CRP, whereas in non-COVID-19 patients, they demonstrated correlations with CRP, troponin I, IL-6, and platelet count." (PMID 40364223, 2025). "By addressing the inflammatory and endothelial dysfunction mechanisms in COVID-19 and non-COVID-19 populations, this study highlights the critical role of inflammation and its markers, such as NLR and IL-6, in endothelial health and potential cardiovascular outcomes." (PMID 40143236, 2025). "Data from COVID-19 trials are reassuring here, showing no increase in bacterial superinfection in those assigned to IL-6 inhibition, but the pathophysiology is very different." (PMID 40819633, 2025). "Elevated serum IL-6 and TNF-α are known predictors of severe COVID-19 and death." (PMID 41329757, 2025). "During acute severe COVID-19 in adults, we observed a negative correlation between galactosylated spike IgG abundances and IL-6 levels and a positive correlation between bisected spike IgG abundances and IFN-γ levels." (PMID 39494457, 2024). "By screening literatures of COVID-19 patients with VTE, this meta-analysis study particularly focused on the elevated levels of IL-6, ferritin and LDH, in order to provide better guide in clinical practice and shed light on the prevention and treatment of VTE among COVID-19 patients." (PMID 38493138, 2024). "Moreover, IL-10, IL6 and TNF-alpha, also biomarkers of COVID-19 severity, were exclusively upregulated in the placebo group at the protein level in serum." (PMID 38649734, 2024). "Inflammatory markers can be used to predict the prognosis of COVID-19 patients.Early studies have reported the impact of C-reactive protein (CRP), procalcitonin (PCT), erythrocyte sedimentation rate (ESR), serum ferritin, IL-6 on the severity of COVID-19." (PMID 38671532, 2024). "The release of proinflammatory cytokines, i.e., TNFα, IL-6, and IFN-β, and the durable increase in activated monocytes and plasmacytoid dendritic cells, promote a state of persistent inflammation in patients with long-term COVID-19 symptoms." (PMID 39124710, 2024). "IL-8, D-dimer, S100B, IL-6, Angpt-2, MMP-8, TNF-R1, u-PAR, u-PA, osteopontin, IL-13, TNF-α, pentraxin-3, P-selectin, fractalkine, and SP-D levels were elevated in critically ill COVID-19 males compared to severe cases." (PMID 39507250, 2024). "Studies show that a positive correlation exists between IL-6 and CRP levels in COVID-19 patients." (PMID 38655258, 2024). "Similarly, matrine, another natural compound, inhibits COVID-19 virus replication and promotes the apoptosis of infected cells by altering TNF-α and IL-6 levels and increasing caspase-3 expression." (PMID 38276618, 2024). "A higher level of IL-6 was observed among female severe COVID-19 patients in this study, though it was not statistically significant." (PMID 38707035, 2024). "Several factors are involved in the recruitment, differentiation, and proliferation of MDSCs, such as IL-6, IL-8, IFN-γ, and TNF-α, all cytokines detected either in SARS infection or following anti-COVID-19 injections and related to the Spike activity as broadly explained in this article." (PMID 38549864, 2024).